CDH4 (cadherin 4)
Diseases named in the same sentence as CDH4 in open-access papers (continued):
Sharing a sentence is not in itself a finding about the gene and the disease.
pancreatic cancer (2 papers, 2022 to 2025). "Similarly, a previous GWAS revealed that two other CDH4 variants (rs1122269 and rs4925193) were associated with significant trends (although not at the level of the current study) in modifying the OS outcomes of patients receiving gemcitabine treatment for pancreatic cancer." (PMID 40535770, 2025). "Moreover, overexpression of CDH4, PTK6, and TFAP2C re-sensitizes pancreatic cancer cells to gemcitabine." (PMID 36289850, 2022).
renal cell carcinoma (2 papers, 2023). "In renal cell carcinoma, the expression of CDH4 is higher than that in normal kidney tissue." (PMID 37237299, 2023).
rhabdomyosarcoma (2 papers, 2021 to 2023). A rare aggressive malignant mesenchymal neoplasm arising from skeletal muscle. "In skeletal muscle, CDH4 has been reported to block myogenesis process and induce myoblast transformation, suggesting a potential oncogenic role in rhabdomyosarcoma." (PMID 34572755, 2021).
schizophrenia (2 papers, 2015 to 2021). A major psychotic disorder characterized by abnormalities in the perception or expression of reality. "Though the CAMs pathway was associated with schizophrenia in pathway level in both Chinese Han and European population, the significant associated CAMs genes in our dataset were different from those significant CAMs genes (HLA-DQA1, CDH4, NRXN1 and CNTNAP2) reported in European population." (PMID 26674772, 2015). "Schizophrenia genes relevant to cell adhesion comprised of several members of the cadherin family CDH22, CDH4, CDH7 and CDH9 as well as the protocadherin PCDH10." (PMID 34859219, 2021).
Ataxia (1 paper, 2020). Ataxia refers to impaired coordination of voluntary muscle movement. "Other genes are related to cytoskeleton remodeling, including Cdh4, Pcdh9, Dock5, Dock3 for the proprioceptors (mutation of Dock3 is known to results in ataxia) and Stom and Pdlim1 for mechanoreceptors, as well as ion channels (Asic1 and Kcnip2 for proprioceptive fate)." (PMID 32826903, 2020).
bladder cancer (1 paper, 2024). "For instance, the knockout of CDH4 significantly diminished the malignant properties of bladder cancer cells." (PMID 38402159, 2024).
breast tumor (1 paper, 2019). "Whereas UBR7 loss promotes breast tumor metastasis, CDH4 overexpression provides only a partial rescue of such phenotypes." (PMID 30923315, 2019).
chronic kidney disease (1 paper, 2019). Impairment of the renal function secondary to chronic kidney damage persisting for three or more months. "HRAECs showed uniquely upregulated genes, including cadherin 4 (CDH4); the protein product of this gene mediates cell–cell adhesion, and mutation of this gene is significantly associated with chronic kidney disease in the Japanese population." (PMID 31856914, 2019).
coloboma (1 paper, 2022). An abnormality in which a part of a structure in one or both eyes is missing. "Novel pathogenic variants in ANK3, BMPR1B, PDGFRA, and CDH4 were identified in 8 unrelated coloboma families." (PMID 35034853, 2022).
depression (1 paper, 2022). "Another GWAS of depression phenotypes in the UK Biobank also identified SNP variants in CDH4 as related variants." (PMID 36704746, 2022). "A multivariate association study demonstrated that a variant in the intron region of CDH4 rs78063755 was associated with Beck Depression Inventory and Migraine Disability Assessment scores." (PMID 36704746, 2022). "Our study showed that the CDH4 intronic polymorphism rs78063755 is a candidate for further studies on migraine with depression in the Han Chinese population, possibly due to its impact on brain segmentation, neuronal growth, and synaptic development." (PMID 36704746, 2022). "Results show that the single nucleotide polymorphism variants of the CDH4 intron region (rs78063755), NTRK3-AS1 downstream region (rs57729223), and between LINC01918 and GPR45 (rs2679891) are suggestively associated with depression." (PMID 36704746, 2022). "Two of which (rs78063755 in CDH4 and rs57729223 in NTRK3-AS1) were also found to be associated with depression in the migraine group." (PMID 36704746, 2022). "This study showed that migraine patients with SNP variants in the intron region of CDH4: rs78063755, downstream region of NTRK3-AS1: rs57729223, and the intergenic region between LINC01918 and GPR45: rs2679891 are suggestively associated with depression in the Han Chinese population in Taiwan." (PMID 36704746, 2022).
Intellectual disability (1 paper, 2022). "Of note, the proband identified in family 8 presented with intellectual disability and postnatal microcephaly; similarly, the cdh4 morphant phenotype at standard dose presented with pleiotropic developmental defects." (PMID 35034853, 2022).
invasive carcinoma (1 paper, 2015). A carcinoma that is not confined to the epithelium, and has spread to the surrounding stroma. "Notably CDH4 is a critical regulator of epithelial phenotype and CDH13 levels are frequently down regulated in invasive carcinoma cells." (PMID 26151554, 2015).
ischemia (1 paper, 2021). A hypoperfusion of the BLOOD through an organ or tissue caused by a PATHOLOGIC CONSTRICTION or obstruction of its BLOOD VESSELS, or an absence of BLOOD CIRCULATION. "Under nonischemic conditions, pericytes expressed Cdh19, Cdh6, Cdh10, Cdh4, Cdh13, and Cdh5; after ischemia, the cadherin genes that were predominantly expressed were Cdh15, Cdh11, Cdh3, and Cdh2." (PMID 33726849, 2021).
leiomyoma (1 paper, 2017). A well-circumscribed benign smooth muscle neoplasm characterized by the presence of spindle cells with cigar-shaped nuclei, interlacing fascicles, and a whorled pattern. "In some cancers, for example, leiomyoma and ovarian carcinoma, CDH4 was treated as proto-oncogene, CDH4 gene expression was upregulated." (PMID 28095912, 2017).
metastatic disease (1 paper, 2025). "However, compared with normal skin samples, the transcriptional activation of the THE1 A element and concomitant downregulation of CDH4 transcription were considerably more pronounced in primary than in metastatic disease." (PMID 40336011, 2025). "Consistent with a role for CDH4 in the metastatic process suggested by findings in other cancer types, we found that transcriptional co-option of THE1 A[CDH4-AS] specifically in SCKM differentiates primary and metastatic disease and is differentially associated with survival in the two subtypes." (PMID 40336011, 2025).
microphthalmia (1 paper, 2022). Congenital or developmental anomaly in which the eyeballs are abnormally small. "cdh4 morphants displayed microphthalmia with a mean eye diameter of 227 ± 19 μm (P < .0001 compared with controls)." (PMID 35034853, 2022).
migraine (1 paper, 2022). "Although CDH4 polymorphism has been reported as a susceptible locus with respect to migraine, the associated mechanism remains unclear." (PMID 36704746, 2022). "In all migraine groups, we found that only MIDAS and BDI scores were significantly associated with a variant in the intron region of CDH4 rs78063755 (P-value = 0.03, 0.048; OR = 1.05, 0.98; 95% confidence interval 1.02–1.08, 0.96–0.99, respectively)." (PMID 36704746, 2022).
oral squamous cell carcinoma (1 paper, 2023). "The function of CDH4 in OSCC (oral squamous cell carcinoma) is unknown." (PMID 37237299, 2023).
papillary thyroid cancer (1 paper, 2021). "In conclusion, these results suggested there may exist an axis between FER1L4, miR-612, and CDH4 which involves the tumorigenesis and aggressiveness of papillary thyroid cancer." (PMID 34289835, 2021).
prostate carcinoma (1 paper, 2021). A carcinoma that arises from epithelial cells of the prostate gland. "CDH4 and PDE4D can be used as early diagnostic markers of gastrointestinal tumor and prostate cancer, respectively." (PMID 34323415, 2021).
tumor (35 papers, 2010 to 2026). "The results indicated their relationship with cell adhesion, junction, and catenin complex, which were all associated with CDH4, a cadherin family member modulating tumor proliferation and migration through the β-catenin pathway as a downstream target." (PMID 38145297, 2024). "Through GSEA of the Hallmark gene set, CDH4 was found positively correlated with multiple tumor-related pathways." (PMID 37237299, 2023). "Twenty-six available blood samples from 42 sporadic CRC cases demonstrating CDH4 copy number loss in non-tumor tissue were collected and assayed with CDH4 copy number qPCR." (PMID 33087131, 2020). "Although the genomic alterations of CRC non-tumor tissues were distinct from those of their corresponding tumors, we noticed that 42 CRCs (11.1%) with CDH4 copy number loss in non-tumor tissue." (PMID 33087131, 2020). "The human CDH4 gene, which encodes the R-cadherin protein, has an important role in cell migration and cell adhesion, sorting, tissue morphogenesis, and tumor genesis." (PMID 28095912, 2017). "Interestingly, our data revealed a CDH4 variant (rs2427043) with a potential impact on the progression of tumours in the HCC population, reflecting an increased risk of downregulated expression of the CDH4 protein." (PMID 40535770, 2025). "Thus, our findings unveil a novel mechanism implicated in tumor metastasis wherein the CDH4/β-catenin complex assumes an indispensable role, underscoring the potential of targeting CDH4 as a viable approach to modulate β-catenin in cancer therapy." (PMID 38402159, 2024). "Vaccination with mutant peptides ZNF169-A275S and CDH4-V456M inhibited tumor growth in an autologous humanized CRC mouse model." (PMID 42087894, 2026). "In contrast, other loci, including RNGTT, the TLR7 and TLR8 loci, and CDH4, are constitutively or inducibly expressed also in healthy tissue and their expression in tumours is downregulated by the independent transcriptional activation of nearby RTEs." (PMID 40336011, 2025). "CDH4 is an intercellular adhesion molecule, which displays a tumor-specific upregulation in HNSCC (vs. adjacent normal tissue)." (PMID 39941730, 2025). "Meanwhile, overexpression of CDH4 promoted tumor formation and enhanced the final tumor weight of subcutaneous tumors compared to the control group." (PMID 38402159, 2024). "Intriguingly, it was discovered that CDH4 predominantly exhibited cytoplasmic distribution within tumor tissues while primarily localized to the cytomembrane in adjacent normal tissues." (PMID 38402159, 2024). "Firstly, in the 17 pairs of PTC tissues collected at our hospital, a higher expression of CDH4 was observed in tumor tissues through IHC analysis." (PMID 38402159, 2024). "Using the RNA-seq data from the Cancer Genome Atlas Program (TCGA), we also found a higher expression level of CDH4 in tumor tissues than in normal tissues." (PMID 38402159, 2024). "The Cadherin family plays a pivotal role in tumor metastasis; however, the involvement of Cadherin 4 (CDH4) in the metastatic cascade remains elusive." (PMID 38402159, 2024). "Based on these two IHC experiments, a notable increase in CDH4 expression and its cytoplasmic localization was observed in tumor tissues when compared to adjacent normal tissues." (PMID 38402159, 2024). "Remarkably, the tumor formation rates were significantly decelerated in the CDH4-silencing groups compared to the control groups, and there was also a notable reduction in tumor weight observed in the CDH4-knockdown groups." (PMID 38402159, 2024). "In order to study the function of CDH4 in OSCC, we used the data of tumor samples given by TCGA to analyze the expression of CDH4 in different tissues and the relationship between CDH4 expression and overall survival rate of patients." (PMID 37237299, 2023).
tumor (continued). "These regions contained tumor-related genes, such as Muc16, Pik3, and Bcl2 in amplification regions and Hras, Notch1, Apc2, Ccnd1, Batf2, Dapk3, Smarca4, Traf2, Traf3, Cdk3, and Cdh4 in deletion regions." (PMID 36424557, 2022). "The identification of new RMS-enriched tumor antigens, such as CDH4, Ephrin A5, and A7, support the clinical relevance of using surfaceomics for target discovery and drug development." (PMID 34572755, 2021). "We detected significant differences in the presence of CDH4 copy number gain between age groups (P < 0.01), tumor locations (P < 0.01), AJCC stages (P < 0.001), differentiation level (P < 0.01) and microsatellite stability status (P < 0.01)." (PMID 33087131, 2020). "These contrasting results can be due to different functions performed by Cdh4 in different tumor types." (PMID 31426573, 2019). "In the group of tumor tissues, the CDH4 mRNA relative value ranged between 0.01 and 2.66 (median 0.08), whereas in the groups of normal tissues, it ranged between 0.03 and 3.01 (median 0.26)." (PMID 28095912, 2017). "CNA gains of suppressor genes are enlisted by gains of HADAC3 in 18 HRO-, COL18A1 in 16 HRO-, TGFBI in 16 HRO- and CDH4 in 15 HRO tumours." (PMID 28486536, 2017). "Notable examples, such as FOXQ1, MAST2, and CDH4, were found to play a role in hair follicle development and human cancer, signal transduction, and tumor repression, respectively." (PMID 23349834, 2013). "Six hits in five genes [AK3 (rs378117), TRPM3 (rs1329774 and rs4745058), CDH4 (rs2427043), LINC00504 (rs76228864), and GRIN2D (rs76754767)] were associated with a risk of tumour progression, whereas variants in HPGD (rs45593131) and RC3H2 (rs2792999) were suggested as protective factors." (PMID 40535770, 2025). "However, the precise role of other classical type I cadherins, such as CDH4 and P-cadherin, in tumor progression remains elusive." (PMID 38402159, 2024). "Additionally, Western blot analysis conducted on six pairs of PTC tissues also revealed an upregulation of CDH4 and a downregulation of E-cadherin in tumor tissues." (PMID 38402159, 2024). "To further evaluate the prediction power of candidate biomarkers that have greater likelihoods of becoming clinically useful markers for NPC diagnosis and for monitoring tumor progression, we built multiple logistic regression models considering the expression of CDH4, STAT4, CYLD and LMP1." (PMID 37393410, 2023). "CDH4 enhanced the self-renewal ability of tumor cells in OSCC." (PMID 37237299, 2023). "CDH4 is epigenetically silenced through promoter hypermethylation in some epithelial cancers, and it may act as a tumor suppressor." (PMID 36685967, 2022). "Of note, the distinct features of FER1L4 and CDH4 in cancer may be caused by the heterogeneity of tumor, suggesting the great potential for FER1L4 and CDH4 as diagnostic biomarkers of PTC." (PMID 34289835, 2021). "Importantly, subcutaneous tumor-formation experiments revealed that knockdown of CDH4 significantly inhibited the formation of subcutaneous tumors of PTC cells." (PMID 34289835, 2021). "While expressions of CDH4 are not changed between tumor and normal tissues (left), CDH4 expression is found to be significantly associated with overall survival (P < 0.01)." (PMID 33087131, 2020). "An alternative explanation could be that Cdh4 expressing tumor cells can form mainly heterophilic interactions with parenchymal cells which expresses only Cdh2." (PMID 31426573, 2019). "Furthermore, CDH4 suppression resulted in down-regulation of E-cadherin (E-cad), which is encoded by CDH1 gene and is a well-known tumor suppressor gene by inhibition of cell proliferation and migration." (PMID 27783992, 2016). "Therefore, if the cytoplasmic localization of CDH4 is perturbed, it could potentially impede the activation of β-catenin signaling, thereby exerting inhibitory effects on tumor metastasis." (PMID 38402159, 2024). "Moreover, Cdh4 expression seems important for tumorigenesis in different tumor types." (PMID 31426573, 2019).
tumor (continued). "Our results suggest that CDH4 might function as a tumor suppressor gene." (PMID 27783992, 2016). "IHC results demonstrated that the expression levels of CDH4, CYLD, and STAT4 were stronger in adjacent basal epithelium compared to that in tumor cells (p < 0.001)." (PMID 37393410, 2023). "Collectively, the composition of CDH4, STAT4, and LMP1 constitutes an ideal model for disease diagnosis as well as for monitoring tumor malignancy." (PMID 37393410, 2023). "IHC analyses showed stronger CDH4, STAT4, and CYLD immunoreactivity in adjacent basal epithelium compared with that in tumor cells (p < 0.001)." (PMID 37393410, 2023). "Specifically, CDH4, SFRP1, and ERF which are indicated to be tumor suppressor genes by the TSGene 2.0 database and have support from the literature as well; however, our method identified them as monotonically increasing genes." (PMID 33273919, 2020). "Remarkably, treatment with Tegavivint significantly impeded tumor formation in CDH4-overexpressing TPC-1 cells, and it also significantly reduced the volume and weight of tumors compared to both control and CDH4-overexpressing groups." (PMID 38402159, 2024). "Because there is a positive correlation between CDH4 and these genes, we think that CDH4 may plays a positive role in EMT, which affects the movement and invasion of tumor cells through EMT pathway." (PMID 37237299, 2023).